KRAS (KRas proto-oncogene, GTPase)
Diseases named in the same sentence as KRAS in open-access papers (continued):
Sharing a sentence is not in itself a finding about the gene and the disease.
endometrial cancer (continued). "Among the included genes and mutations, we have identified and validated KRAS, PIK3CA and FGFR2 to be the most frequently mutated oncogenes in endometrial cancer." (PMID 23300780, 2012). "Our previous screening of a smaller number of endometrial cancer patients identified somatic mutations in FGFR2, KRAS, PIK3CA, PTEN, PT53 and CTNNB1." (PMID 23300780, 2012). "Mutations in multiple oncogenes including KRAS, CTNNB1, PIK3CA and FGFR2 have been identified in endometrial cancer." (PMID 22383975, 2012). "Our results emphasize the potential for targeting FGFR2, KRAS and PIK3CA mutations in endometrial cancer for development of novel therapeutic strategies." (PMID 23300780, 2012). "Additional work is needed to identify the mechanistic basis and biological significance of the mutual exclusivity of KRAS and CTNNB1 mutations in endometrial cancer." (PMID 22383975, 2012). "Mutations in KRAS, especially in codon 12, result in the constant activation of downstream pathways like MAPK and PI3K/AKT, leading to uncontrolled cell growth and tumorigenesis in endometrial cancer." (PMID 40560289, 2025). "Furthermore, patients with NSMP endometrial cancer and combined mutant KRAS and wt ARID1A who underwent initial surgery have a poor prognosis." (PMID 36797358, 2023). "Indeed, even other gynecological epithelial cancers such as endometrial cancer are associated with the presence of numerous driver gene mutations in PIK3CA, ARID1A, PTEN, KRAS, CTNB1, and FGFR." (PMID 35740550, 2022). "However, we also explored less well characterized KRAS landscapes such as in endometrial cancer, where KRAS G12V and G12D are predominant, as well as small bowel and appendiceal cancers, cholangiocarcinoma, and others." (PMID 36494601, 2022). "For example, the presence of a PTEN mutation, especially when mutated concurrently with a PIK3CA and KRAS mutation, may predict sporadic MMR deficient endometrial cancer; the wild-type status of PTEN may be associated with LS-associated endometrial cancer." (PMID 35884469, 2022). "Whole genome and target sequencing of endometrial glands have identified extensive clonal expansions in individuals without endometrial cancer, with more frequent somatic mutations seen in KRAS and PIK3CA specifically." (PMID 36311816, 2022). "While Type II endometrial cancers tend to metastasize and are hormone-independent, Type I endometrial cancers are generally considered endocrine-dependent and commonly have mutations in PTEN, members of the PI3K/AKT pathway, and KRAS." (PMID 34885064, 2021). "While there are several epigenetic biomarkers for endometrial cancer (p52, KRAS, VEGF." (PMID 30679932, 2019). "The authors conclude that analysis of PTEN and KRAS status in the epithelium of the tumor, and PR expression in the stroma, may be suitable biomarkers for progesterone sensitivity in endometrial cancer." (PMID 31827798, 2019). "Most molecular studies in endometrial cancer have focused on the most common form, uterine endometrioid carcinoma (UEC), which is primarily driven by PTEN loss and mutations in FGFR2, ARID1A, CTNNB1, PIK3CA, PIK2R1, and KRAS." (PMID 26170901, 2015).
endometrial cancer (continued). "Although the KRAS-variant was not a predictor of overall endometrial cancer risk, it was enriched in patients with type 2 cancers, with a prevalence of 24.3%." (PMID 24732316, 2014). "In addition, type I endometrial cancers are often hormone receptor positive with PTEN and KRAS mutations." (PMID 23300780, 2012). "We can speculate that the pattern of mutual exclusivity of FGFR2 and KRAS suggests that the role of these two genes in endometrial cancer initiation is likely to be through activation of the MAPK signaling pathway." (PMID 22383975, 2012). "One finding that may have implications for understanding the biology underlying endometrial cancer is the hereto-unrecognized mutual exclusivity of CTNNB1 and KRAS mutations in this cohort." (PMID 22383975, 2012). "PIK3CA activation is reported in 26–36% of endometrial carcinoma and may coexist with PTEN (15–27%) and KRAS mutations suggesting that the PIK3CA mutations cooperate with these alterations in malignant transformation." (PMID 20368795, 2010). "However, there is no consensus on how KRAS mutation affects the prognosis of endometrial cancers, with only a few reports associating it with poor prognosis and aggressive clinical behaviour." (PMID 36797358, 2023). "Interestingly, KRAS amplification was also found at higher frequency in endometrial cancer metastases versus primary tumors, suggesting that KRAS amplification may be a potential mechanism for metastasis formation and cancer progression." (PMID 24874471, 2014). "Additionally, ERK activation is seen in endometrial cancers without mutations in KRAS and FGFR2 (and our unpublished data)." (PMID 23941783, 2013). "Although transcriptional signature pattern according to histologic grade did not identify any distinct subgroups linking any of the mutations to phenotype, PIK3CA, KRAS and FGFR2 mutations may still be of relevance for targeting novel therapeutics in endometrial cancer." (PMID 23300780, 2012). "We also analyzed the differences in immune characteristics between KRAS mutant MLA and KRAS mutant endometrial cancer in TCGA." (PMID 40740763, 2025). "For example, endometrial cancer is characterized by intrachromosomal amplification of ESR1, KRAS, PIK3CA, ERBB2, TERC, MYC, CCNE1." (PMID 41415205, 2025). "In this study, we found significantly elevated mRNA expression levels of the oncoprotein KRAS, along with two replicative stress markers, ATR and CHEK1, in samples of endometrial carcinomas of endometrium (ECE) from patients with relapse." (PMID 38669256, 2024). "Meanwhile, 4/12 (33.3%) endometrial cancer cases had alterations in PI3K pathway genes (PIK3CA, PTEN, and KRAS)." (PMID 36765826, 2023). "Patients with NSMP (as identified by an IHC-based on molecular classifier) endometrial cancer with mutant KRAS and wt ARID1A showed poor RFS compared with those with other KRAS/ARID1A statuses." (PMID 36797358, 2023). "In endometrial cancers, high TMB was enriched in KRAS G13D, G12D, G12C, and G12A (45%, 34%, 30%, and 31%) compared to G12V and WT (21% and 16%, p < 0.05 for all comparisons)." (PMID 36494601, 2022). "Furthermore, KRAS mutation is not unique to MLA in endometrial cancer." (PMID 35865471, 2022).
endometrial cancer (continued). "In summary, inhibition of MEK with cobimetinib alone or in combination with PI3K inhibitors (pictilisib and apitolisib) could be a promising treatment modality, not just for endometrial cancer patients with mutated KRAS, but also for those with retained PTEN expression." (PMID 29426295, 2018). "Another study made similar experiments, but this time using 13 endometrial cancer cell lines (possessing at least one alteration of PTEN, PIK3CA or KRAS) and xenografts in nude mice in vivo." (PMID 28008141, 2017). "Elevated KRAS protein levels are characteristic of poorly differentiated (G3) endometrial carcinomas with deep myometrial invasion in patients without recurrence." (PMID 38669256, 2024). "Elevated levels of KRAS protein are characteristic of poorly differentiated grade tumors with deep myometrium invasion of endometrial carcinomas in the group of patients without recurrence in anamnesis." (PMID 38669256, 2024). "have suggested that dysregulation of complex regulatory mechanisms are involved in ERK activation in endometrial cancers, where there is similarly a lack of ERK activation in the presence of KRAS mutations." (PMID 26864819, 2016). "Importantly, we found that the CTNNB1-enriched subgroup harbored frequent PTEN mutations but not for KRAS mutations, suggesting that PTEN loss but not KRAS mutations might enhance the CTNNB1-induced genetic program to promote tumor development in endometrial cancer." (PMID 26431491, 2015). "Statistically higher (2.9-fold) levels of KRAS, and elevated expression of pATR (2.8 fold) and pCHEK1 (1.3-fold) proteins were detected in poorly differentiated endometrial carcinomas in the group without recurrences compared to neoplasms with high and moderate grades of differentiation." (PMID 38669256, 2024). "The mRNA expression levels of KRAS, ATR, CHEK1 genes in endometrial cancer tissue samples at stage I with and without recurrence in anamnesis." (PMID 38669256, 2024). "Mismatch repair (MMR) signature was rare in non-Sq NSCLC but common in KRASm and KRAS WT PDAC, CRC and endometrial cancers, although relatively less frequent in KRAS G12C CRC relative to other subgroups." (PMID 36494601, 2022). "This is in consistent with a recent report showing that this pathway is frequently activated independent of the status of KRAS and BRAF in endometrioid-type endometrial cancer." (PMID 23820584, 2013).
squamous cell carcinoma (139 papers, 2001 to 2026). A carcinoma arising from squamous epithelial cells. "EGFR and KRAS are two of the most mutated genes in adenocarcinomas, while these genes rarely change in squamous cell carcinoma." (PMID 39201328, 2024). "Four patients with squamous cell carcinoma had molecular abnormalities atypical for this histological type, suggesting a secondary adenocarcinomatous contingent: a KRAS G12C mutation, a KRAS amplification, a STK11 mutation and an ALK mutation." (PMID 39764418, 2024). "Uranium miners are exposed to several carcinogens and most of them were smokers and had adenocarcinomas, which harbour more KRAS mutations than found in squamous cell carcinoma in lung." (PMID 36291897, 2022). "KRAS mutations correlate with histology: transversions, more frequently develop adenocarcinoma while transitions more frequently have squamous cell carcinoma." (PMID 34918209, 2021). "The PI3K/AKT and MAPK pathways are frequently activated in cancers, including KRAS mutant NSCLCs, and around 30% of adenocarcinomas (ACs) and 3% of squamous cell carcinomas (SCCs) contain KRAS mutations." (PMID 31772293, 2019). "Among the five histological types, the mutation rates of KRAS were 34.3% in adenocarcinoma, 60.0% in mucinous adenocarcinoma, 0% in low adhesion carcinoma, 50% in signet-ring cell carcinoma, and 50% in squamous cell carcinoma, respectively." (PMID 30416987, 2018). "Recently, also tumour-specific mutations have been reported, such as EGFR exon 20 mutations in 88% inverted papilloma and in 77% of squamous cell carcinoma associated with inverted papilloma, and KRAS mutations in oncocytic papillomas." (PMID 29507386, 2018). "Using sequential in vivo recombination, we find that FoxA1/2 loss in established KRAS-driven neoplasia originating from SPC-positive alveolar cells induces keratinizing squamous cell carcinomas." (PMID 30475207, 2018). "A high-throughput genotyping platform showed that squamous cell carcinoma and adenocarcinoma have distinct molecular profiles; KRAS mutations were identified only in adenocarcinoma and EGFR mutation was detected only in squamous cell carcinoma." (PMID 26660311, 2015). "KRAS mutations were only significantly associated with the histology type (non-squamous cell carcinoma) (p=0.0091)." (PMID 23951022, 2013). "The prevalence of KRAS mutations was 28.8% (19 out of 66), where the majority was found in adenocarcinomas and a small proportion in squamous cell carcinoma (SCC, 10.5%)." (PMID 26316935, 2012). "Biochip hybridization identified 17 (21%) samples to carry a KRAS mutation of which 16 (33%) were adenocarcinomas and 1 (3%) was a squamous cell carcinoma." (PMID 22272089, 2011). "All confirmed somatic mutations were found in adenocarcinomas except for a Gly12Asp mutation in KRAS in a squamous cell carcinoma." (PMID 17487277, 2007). "The Transformation of pathology from adenocarcinoma to squamous cell carcinoma occurs in patients of solid tumors with KRAS mutations, and genetic alterations in cell cycle regulators is reported, causing cell cycle dysregulation to attenuate the therapeutic response of KRAS inhibitor." (PMID 36675641, 2023). "Furthermore, we also observed that smokers were more frequently to have squamous cell carcinoma and KRAS mutations, and less frequently to have EGFR L858R." (PMID 35061839, 2022). "Similarly, squamous cell carcinoma, KRAS mutations, and EGFR L858R mutation were more commonly found in males than females." (PMID 35061839, 2022). "In addition, smokers were more likely to have squamous cell carcinoma and KRAS mutation and less likely to have EGFR L858R, which were also confirmed after standardization of gender except KRAS mutations." (PMID 35061839, 2022).
squamous cell carcinoma (continued). "Among squamous-cell carcinomas, 5.3% (n = 1 out of 19) were KRAS-mutated (p.Gly12Asp)." (PMID 33956502, 2021). "Moreover, several previous studies assessing the KRAS mutation status in primary tumors have suggested that KRAS mutation is uncommon in squamous cell carcinomas." (PMID 21414214, 2011). "Squamous cell carcinoma was identified in 96 (48%) patients, with EGFR mutations present in 35 (18%), and KRAS mutations in 65 (34%)." (PMID 41245885, 2025). "In contrast, our study included a significant portion of patients with squamous cell carcinoma and those with EGFR and KRAS mutations, which are likely contributing to this difference and warrant further clinical and translational research for confirmation." (PMID 41245885, 2025). "In our study, PD-L1 expression was significantly higher in squamous cell carcinomas and lower in adenocarcinomas, and was positively associated with MET and KRAS mutations, as well as the wild-type EGFR gene state." (PMID 38394518, 2024). "The distributions of these mutations were similar across both cancer histologies, with the exception of oncogenic KRAS mutations, which were almost exclusive to LUAD apart from a single patient with squamous cell carcinoma with a KRASG12C mutation." (PMID 39113608, 2024). "In the present study, coexisting KRAS and PIK3CA mutations were found in 17.1% of patients; in more than half with squamous cell carcinoma." (PMID 37108122, 2023). "The downregulation of miR-3182 in response to treatment has been validated in human epidermoid carcinoma cells that have undergone photodynamic treatment, as well as sorafenib-treated mutant KRAS colorectal cells." (PMID 35008424, 2022). "As well, KRAS alterations are more frequent in adenocarcinoma (32%) than squamous cell carcinoma (4%)." (PMID 35251972, 2022). "Compared with KRAS WT, both transversions and transitions were significantly more common in men, ever-smokers, and non-squamous cell carcinoma patients." (PMID 36348317, 2022). "Although rare, the definite percentage of PD-L1 expression levels in KRAS mutant squamous cell carcinoma needs to be explored." (PMID 36136862, 2022). "One mutation was detected in KRAS (G12/G13) and 3 in EGFR (2 L858R, 1 S768I) for three patients with squamous cell carcinoma with a smoking history, and one patient with SCLC." (PMID 36413862, 2022). "The frequency of adenocarcinomas (40%) and squamous cell carcinomas (45%) was similar in KRAS wildtype tumors." (PMID 34413420, 2021). "Adenocarcinoma tumors were mostly pan-wild type (36.5%), KRAS mutated (35.4%), and EGFR mutated (16.3%) while squamous cell carcinoma tumors were even more predominantly pan-wild type (85.5%)." (PMID 34917263, 2021). "Among the three most common histological subtypes of cervical cancer (squamous cell carcinoma (SCC), adenocarcinoma (AC), and adenosquamous carcinoma (ASC)) KRAS mutations are reported to occur more frequently in AC than SCC." (PMID 33736612, 2021).